NEUROG2 (neurogenin 2)
Description:
Transcriptional regulator. Involved in neuronal differentiation. Activates transcription by binding to the E box (5'-CANNTG-3').
Synonyms: NGN-2; bHLHa8; ATOH4; NGN2; Math4A
Tractability: No criterion of Open Targets' tractability assessment is met for any kind of drug.
Gene: Protein-coding gene on chromosome 4 (112,513,516 to 112,516,180, reverse strand). Ensembl gene ENSG00000178403.
Subcellular location: Nucleus
Gene Ontology:
Molecular function: protein binding; sequence-specific double-stranded DNA binding; DNA-binding transcription factor activity, RNA polymerase II-specific; E-box binding; protein dimerization activity
Biological process: axon development; forebrain development; positive regulation of transcription by RNA polymerase II; sensory organ development
Cellular component: chromatin; nucleus
Genetic constraint (gnomAD): Loss-of-function variants: 0 observed, 1.76 expected, observed/expected ratio (o/e) 0, 90% interval 0 to 1.45. That is too few expected variants to judge how well the gene tolerates losing a copy. Missense variants: 289 observed, 265.95 expected, observed/expected ratio (o/e) 1.09, 90% interval 0.99 to 1.2. Synonymous variants: 158 observed, 126.52 expected, observed/expected ratio (o/e) 1.25, 90% interval 1.1 to 1.42.
Homologues: Orthologues: chimpanzee NEUROG2 (100% identical), macaque NEUROG2 (99% identical), dog NEUROG2 (94% identical), rabbit NEUROG2 (94% identical), pig NEUROG2 (92% identical), rat Neurog2 (85% identical), mouse Neurog2 (84% identical), Drosophila melanogaster tap (28% identical), Caenorhabditis elegans ngn-1 (19% identical), Drosophila melanogaster ato (15% identical), Drosophila melanogaster Oli (14% identical), Drosophila melanogaster amos (14% identical), and 4 more. Paralogues in human: NEUROG1 (33% identical), NEUROG3 (31% identical), NEUROD1 (27% identical), NEUROD6 (27% identical), NEUROD4 (26% identical), NEUROD2 (25% identical), ATOH1 (19% identical), BHLHA15 (18% identical), OLIG1 (18% identical), OLIG2 (17% identical), BHLHE23 (17% identical), OLIG3 (16% identical), and 3 more.
Diseases named in the same sentence as NEUROG2 in open-access papers:
NEUROG2 is named in the same sentence as 54 diseases in open-access papers, as found by Europe PMC text mining. Sharing a sentence is not in itself a finding about the gene and the disease. The quoted sentences say what the papers report.
glioma (9 papers, 2012 to 2023). A benign or malignant brain and spinal cord tumor that arises from glial cells (astrocytes, oligodendrocytes, ependymal cells). "Single TFs have also been successful in reprogramming glioma cells into neurons, with lentiviral introduction of Neurog2 demonstrating successful reprogramming of human glioma cells into neuron-like cells and decreased glioma growth with improved survival of tumor-bearing mice." (PMID 36289861, 2022). "Second, Ascl1 and Neurog2 triggered distinct transcriptional changes in human glioma cells, which may have explained different neuronal fates after conversion." (PMID 33755378, 2021). "Overexpression of bHLH transcription factors such as Neurog2 (NGN2) and ASCL1 has demonstrated the ability to transform human glioma cells into neuron-like cells in culture." (PMID 37582760, 2023). "Here, we show that neurogenin 2 (NGN2, also known as NEUROG2) synergizes with sex-determining region Y-box 11 (SOX11) to very efficiently convert human glioma cells to terminally differentiated neuron-like cells in both cell culture and adult mouse brains." (PMID 25321470, 2014). "Recent study has showed that cultured human glioma cells could be converted into neuron-like cells by overexpression of three neurogenic transcription factors ASCL1, BRN2 and NGN2 (Neurogenin-2)." (PMID 31212628, 2019).
Stroke (7 papers, 2018 to 2023). Sudden impairment of blood flow to a part of the brain due to occlusion or rupture of an artery to the brain. "Notably, a study of focal ischemia, a well-characterized stroke model, further enhanced the ability of Neurog2 to drive glial conversion to mature DCX-/NEUN+ iNs compared to the immature DCX+ iNs that predominated in the uninjured brain." (PMID 34291049, 2021).
glioblastoma (4 papers, 2021 to 2024). The most malignant astrocytic tumor (WHO grade IV). "Human glioblastoma cells can be phenotypically reprogrammed into neuron‐like cells through the forced expression of NEUROG2 and SOXC factors." (PMID 39390804, 2024). "Consistent with their developmental functions, our transcriptome results showed that Ascl1 and Neurog2 elicited different neurogenic programs in human glioblastoma cells." (PMID 33755378, 2021). "First, we discovered significant activation of neuronal genes induced by Neurog2 in human glioblastoma cells." (PMID 33755378, 2021). "In summary, human glioblastoma cells were efficiently reprogrammed into neuron-like cells through in vivo ectopic expression of the Neurog2 neural transcription factor in a xenograft mouse model." (PMID 33755378, 2021). "Neurog2 and ASCL1, both basic helix loop helix (bHLH) transcription factors, have been shown to reprogram glioblastoma cells into neuron-like cells." (PMID 37582760, 2023). "To identify the underlying mechanism of the glioblastoma cell-to-neuron conversion process, we performed RNA-sequencing (RNA-seq) and transcriptome analyses of GBM cells after Neurog2 or Ascl1 overexpression, with GFP alone serving as the control group (3 replicates for each group)." (PMID 33755378, 2021).
Alzheimer disease (3 papers, 2017 to 2025). A progressive, neurodegenerative disease characterized by loss of function and death of nerve cells in several areas of the brain leading to loss of cognitive function such as memory and language. "Additionally, the signatures of several transcription factors, such as Olig2, NeuroD1, TCF4, and NeuroG2, were found to be enriched in Alzheimer’s disease-associated accessible chromatin regions within hippocampal tissues." (PMID 40483385, 2025).
breast carcinoma (3 papers, 2018 to 2022). "The role of MATN4, SLC6A17, and NEUROG2 genes in breast cancer is currently unknown, but they play a role in other cancers, which may be an inspiration for future breast cancer gene research." (PMID 36553681, 2022).
neuroblastoma (3 papers, 2022 to 2025). Neuroblastoma (NB) is the most common solid, extracranial childhood tumor. "Compared to baseline control values, NEUROG2 elevated luciferase activity in SHSY-5Y human neuroblastoma cells using either the PPP1R17-HAR or -TSS reporters." (PMID 39680368, 2025).
virus infection (3 papers, 2019 to 2024). "In addition, quantitative analyses showed that ATOH7 and Neurog2 virus infection altered cell cycle distributions among progenitors compared to controls." (PMID 34055784, 2021).
mediastinal tumours (2 papers, 2024 to 2025). "HN-PG and the suspected non-chromaffin mediastinal tumours had low expression of the chromaffin cell marker CARTPT24, neural transcriptional regulators (TFAP2B, TOX3, GATA3, POU4F, NEUROG2, PAX2), HOX genes (HOXA1-10, HOXB4, HOXB6-9, HOXC4-HOXC13), and the long non-coding RNA HOTAIR." (PMID 40097403, 2025). "HN-PG and the suspected non-chromaffin mediastinal tumours had low expression of the chromaffin cell marker CARTP24, neural transcriptional regulators (TFAP2B, TOX3, GATA3, POU4F, NEUROG2, PAX2), HOX genes (HOXA1–10, HOXB4, HOXB6–9, HOXC4-HOXC13), and the long non-coding RNA HOTAIR." (PMID 38978571, 2024).
developmental delay (1 paper, 2023). "Developmental delay, in this case, might be caused due to NEUROG2 haploinsufficiency." (PMID 36816813, 2023).
maturity-onset diabetes of the young (1 paper, 2024). "Among the six detected motifs, four were highly similar to the known consensus motifs HNF1B (P = 10−38), NEUROG2 (P = 10−32), FOXA1 (P = 10−23), and RFXDC2 (P = 10−15), among which HNF1B is known to be responsible for maturity-onset diabetes of the young (MODY) type 5." (PMID 38876803, 2024).
mental retardation (1 paper, 2013). "In addition to ASCL1 and NEUROG2, other neurodevelopmental transcriptional regulators such as, MEF2C (syndromic mental retardation) and ZEB2 (MWS) were also differentially expressed in TCF4-depleted cells." (PMID 24058414, 2013).
retinoblastoma (1 paper, 2019). A malignant tumor that originates in the nuclear layer of the retina. "Meanwhile, if oscillatory gene expression in some undifferentiated cells/RPCs does not stop due to pathological events (e.g., mutations in genes regulating the stability of mRNA and proteins of genes like Notch1, Hes1, Dll1, Ascl1, Neurog2, etc.), these cells may begin retinoblastoma formation." (PMID 31607861, 2019).
infection (16 papers, 2010 to 2025). The state of being infected such as from the introduction of a foreign agent such as serum, vaccine, antigenic substance or organism. "At 12 days post infection (dpi), Ascl1 and Neurog2 shared a similar neuronal induction efficiency, about 50% of GFP+ cells (data not shown)." (PMID 35832093, 2022). "Immunostaining results showed that mCherry and Neurog2 were co-expressed at 3 days post infection (3 DPI)." (PMID 33649354, 2021). "In this study, AAV vector was used to express Neurog2 under the direct control of a human GFAP promoter for the specific astrocytes infection." (PMID 33649354, 2021). "Interestingly, LV-NEP but not LV-AEP infection caused a twofold increase of endogenous NEUROG2-expressing cells as well as elevated the median expression level, suggesting that Neurog2 positively regulates endogenous NEUROG2 expression." (PMID 34055784, 2021). "Both virally expressed ATOH7f and Neurog2 increased the number of endogenous ATOH7-expressing cells from 9.1 to 22.0% among total cells, and LV-NEP infection also increased the median ATOH7 expression level." (PMID 34055784, 2021). "Inoculation of human-induced pluripotent stem cell (hiPSC)-derived neurogenin-2 (Ngn2) neuronal co-cultures, consisting of neurons and astrocytes that both lack MeV receptors CD150 and nectin-4, led to productive infection and replication of both rMeVSSPE-F and rMeVF-N465I." (PMID 38329336, 2024).
cancer (8 papers, 2021 to 2025). A tumor composed of atypical neoplastic, often pleomorphic cells that invade other tissues. "To explore this idea, we reanalyzed six NEUROD2 and NEUROG2 induction experiments across diverse cell types, including embryonic stem cells (ESCs), P19 carcinoma cells and embryonic fibroblasts." (PMID 39494521, 2024).
neurodegenerative disease (4 papers, 2020 to 2025). A disorder of the central nervous system characterized by gradual and progressive loss of neural tissue and neurologic function. "Our study shows that elevating ATOH7 and Neurog2 expression in human retinal organoids significantly enhances early retinogenesis, which can serve as a useful approach to produce authentic human RGCs for studying development and degenerative diseases." (PMID 34055784, 2021).
neurological disease (3 papers, 2024 to 2025). "Cellular overexpression of the pro-neural transcription factor Neurogenin-2 (NGN2) – to promote differentiation of iPSCs into excitatory neurons – is a popular and robust model to study neurological disease and development of neuronal networks." (PMID 39632788, 2024).
NEUROG2 also shares sentences with these, for which no sentence is quoted: tumor (11 papers); Cerebral ischemia (4); Parkinson disease (3); Anxiety (2); brain injury (2); brain tumor (2); Cognitive impairment (2); embryonal carcinoma (2); ischemia (2); malignant glioma (2); schizophrenia (2); amyotrophic lateral sclerosis (1); Angelman syndrome (1); astrocytomas (1); autism (1); autism spectrum disorder (1); Axenfeld-Rieger syndrome (1); behavioral disorder (1); dementia (1); depression (1); hepatocellular carcinoma (1); Hyperglycemia (1); inflammatory bowel disease (1); injury (1); iris coloboma (1); ischemic stroke (1); memory impairment (1); metabolic disease (1); motor neuron diseases (1); Mowat-Wilson syndrome (1).
A further 8 diseases each share a sentence with NEUROG2 in 1 paper.